ZDHHC19 (zDHHC palmitoyltransferase 19)
Diseases named in the same sentence as ZDHHC19 in open-access papers (continued):
Sharing a sentence is not in itself a finding about the gene and the disease.
breast carcinoma (1 paper, 2025). "Interestingly, our study also revealed that ZDHHC19 is upregulated in various cancer types, including bladder and breast cancer, which aligns with previous research demonstrating its role in tumor progression and modulation of the immune microenvironment." (PMID 40666706, 2025).
glioblastoma (1 paper, 2023). The most malignant astrocytic tumor (WHO grade IV). "ZDHHC19‐mediated SMAD family member 3 (Smad3) palmitoylation at Cys421 enhances activation of the transforming growth factor (TGF) signaling pathway, and Smad3 interaction with E1A binding protein P300 (EP300) promotes mesenchymal‐like transition in the mesenchymal subtype of glioblastoma (GBM)." (PMID 36018061, 2023).
lung squamous cell carcinomas (1 paper, 2022). "ZDHHC19, a key enzyme in the DHHC family, has been reported to be upregulated in human lung squamous cell carcinomas, and high ZDHHC19 expression could promote STAT3 activation through S-Palmitoylation." (PMID 35297315, 2022).
male infertility (1 paper, 2021). The inability of the male to effect fertilization of an ovum after a specified period of unprotected intercourse. "To understand the underlying causes of male infertility of Zdhhc19 KO mice, we assessed the motility of sperm isolated from the epididymis by CASA." (PMID 34445597, 2021). "Because Zdhhc19 KO spermatozoa contained potential defects in their head formation and did not respond well to A23187, it is plausible that impaired ability of Zdhhc19 KO sperm in induced acrosome reaction is a primary cause for their male infertility." (PMID 34445597, 2021). "Given that Zdhhc19 KO mice were sterile yet with normal spermatogenesis, reduced sperm motility, and abnormal acrosome reaction, male infertility can be caused by failure of spermatozoa to migrate through the female uterotubal junction (UTJ) due to low sperm motility." (PMID 34445597, 2021). "To further distinguish the potential causes for male infertility upon Zdhhc19 KO, we performed the in vitro fertilization (IVF) assay, which can exclude the contribution of failure in UTJ migration of Zdhhc19 KO sperm." (PMID 34445597, 2021).
pancreatic cancer (1 paper, 2025). "Furthermore, ZDHHC19 showed a significant positive correlation with immune microenvironment scores in many cancers, especially pancreatic cancer, likely due to its involvement in immune cell chemotaxis." (PMID 40666706, 2025).
primary immunodeficiency (1 paper, 2020). "ZDHHC19, 15, 3, 21, 23, and 9 were involved in primary immunodeficiency and natural killer cell-mediated cytotoxicity." (PMID 33364189, 2020).
viral infections (1 paper, 2021). "ZDHHC19, zinc finger DHHC-type palmitoyltrasferase 19, is known to be associated with some viral infections." (PMID 34442377, 2021).
cancer (5 papers, 2021 to 2025). A tumor composed of atypical neoplastic, often pleomorphic cells that invade other tissues. "Notably, ZDHHC19 has been implicated in promoting immune evasion in cancer by influencing processes such as antigen presentation suppression and Treg recruitment." (PMID 40666706, 2025). "In addition to its potential role in immune modulation, ZDHHC19 has been implicated in various cancers, where it is thought to regulate tumor progression and immune cell interactions within the tumor microenvironment." (PMID 40666706, 2025). "ZDHHC19 exhibited inconsistent correlations with immune cells across different cancer types." (PMID 40666706, 2025). "In several human cancers, signal transducer and activator of transcription 3 (STAT3) is palmitoylated by zinc finger DHHC-Type palmitoyltransferase 19 (ZDHHC19), a palmitoyl acyltransferase, at the SRC homology 2 (SH2) domain, which promotes its dimerization and transcriptional activation." (PMID 35004688, 2021). "For example, follicular helper T cells were positively correlated with ZDHHC19 expression in most cancers, while CD8+ T cells showed a marked lack of correlation, suggesting that ZDHHC19 requires personalized consideration in guiding immune responses across various cancers." (PMID 40666706, 2025).
tumor (4 papers, 2022 to 2025). "zDHHC19 is a target of the tumor suppressor miR‐940 and zDHHC19 overexpression mitigated the suppression of proliferation, migration, and invasion induced by miR‐940." (PMID 39429488, 2024). "Zinc finger Asp-His-His-Cys palmitoyl-acyltransferase 19 (ZDHHC19) is a key enzyme in protein palmitoylation and plays crucial roles in tumor progression." (PMID 35297315, 2022). "In order to determine whether ZDHHC19 could promote tumor growth in vivo, 143B cells transfected with sh-ZDHHC19 or sh-NC were injected into nude mice, respectively." (PMID 35297315, 2022). "Taken together, all these suggested that ZDHHC19 could accelerate tumor growth and metastasis in vivo." (PMID 35297315, 2022). "In addition, the IHC data revealed that ZDHHC19 and Ki-67 protein expression were weaker after ZDHHC19 silencing, indicating that the proliferative ability of tumor was impaired." (PMID 35297315, 2022). "Interestingly, ZDHHC19 silencing did not affect the proliferation ability of non-tumor cells." (PMID 35297315, 2022).
infection (3 papers, 2021 to 2025). The state of being infected such as from the introduction of a foreign agent such as serum, vaccine, antigenic substance or organism. "Drawing from previous studies, we speculate ZDHHC19 overexpression may link to immune-paralysis and immunosenescence, increasing secondary infection risk and mortality." (PMID 38167131, 2024). "ZDHHC19 mRNA turned out to be a robust marker of infection, and it was more profoundly induced in bacterial infections compared to viral ones." (PMID 40282319, 2025). "Additionally, our association analysis highlighted significant correlations between ZDHHC19 expression and clinical parameters such as procalcitonin, neutrophil count and INR, reinforcing the role of ZDHHC19 in the systemic response to infection." (PMID 40282319, 2025). "A major immune function of ZDHHC19 is to facilitate activation of STAT3 upon cytokine stimulation, which is important for immune signaling in infection and inflammation." (PMID 34442377, 2021).
ZDHHC19 also shares sentences with these, for which no sentence is quoted: bone tumor (1 paper); colorectal cancer (1); endometrial carcinoma (1); Obesity (1); prostate carcinoma (1); schizophrenia (1); uterine sarcoma (1); uveal melanoma (1).